EGFR (epidermal growth factor receptor)
Diseases named in the same sentence as EGFR in open-access papers (continued):
Sharing a sentence is not in itself a finding about the gene and the disease.
cancer (continued). "However, cancer patients receiving EGFR inhibitors often develop eventual resistance to the treatments." (PMID 34375550, 2021). "HLX07 is therefore hypothesized to possess improved safety and at least comparable anti-cancer efficacy in patients comparing to current approved anti-EGFR mAbs." (PMID 33713216, 2021). "Furthermore, expression of miR-133 has been frequently linked to reduced cell proliferation and diminished invasive ability of cancer cells via downregulation of EGFR, FOXC1, FOXQ1 and PSEN114, 22-24." (PMID 34335946, 2021). "In addition, Src expression and activation in cancer cells always occurs after alterations to one or more of its activators, such as EGFR." (PMID 34147083, 2021). "The compensation of alternative signaling pathways in various oncogenic mutations and different cell contexts, including aberrant EREG expression, may lead to the unfavorable outcomes of anti-EGFR therapies in various cancer cells." (PMID 34884633, 2021). "BPA-mediated anticytotoxicity in cancer cells also involves EGFR signaling pathway." (PMID 33666848, 2021). "Clinical evidence provided through case reports and clinical trials suggest that therapeutics targeting EGFR may alleviate pain in both cancer patients and non-cancer patients afflicted with neuropathic pain." (PMID 34054523, 2021). "As it has widely been described, several clinical trials have shown that KRAS mutations in cancer involve a lack of response to targeted anti-epidermal growth factor receptor (EGFR)-based therapies." (PMID 33664850, 2021). "However, acquired and innate resistances have precluded current anti-EGFR agents from offering sustainable benefits to initially responsive cancers and benefits to EGFR-positive cancers that are inherently resistant." (PMID 34638405, 2021). "Moreover, we demonstrated that SPINK1 secreted from hypoxic cancer cells has the potential to induce radioresistance of the surrounding oxygenated cells in a paracrine manner through activation of the EGFR-mediated and Nrf2-mediated antioxidant pathway." (PMID 34747365, 2021). "Inhibition of the EGFR signaling pathway and the expression of cancer stemness marker genes may partially account for the antitumor effects of this compound." (PMID 34879870, 2021). "Epidermal growth factor receptor (EGFR), a glycoprotein belonging to the tyrosine kinase receptor family, has been implicated in the development, progression and severity of several human cancers, and is an attractive target for therapeutic intervention." (PMID 33462221, 2021). "Thus, we used a Gefitinib for comparing the efficacy of anti-cancer effects with 13f a new EGFR inhibitor." (PMID 33639651, 2021). "Hence, the interaction of SPINK1 with EGFR has attracted attention for its potentially pivotal biological functions, especially in modulating cancer progression." (PMID 33916984, 2021). "The existence of a cell-intrinsic program through which AXL-positive/Erlotinib-resistant cells emerge infers the need of treating tumors harboring EGFR-oncogenic mutations upfront with combinatorial treatments targeting both AXL-negative and AXL-positive cancer cells." (PMID 34254585, 2021). "Finally, EGFR, which is a protein overexpressed on multiple cancer cells, can also be a reliable target for peptides to deliver different therapeutics." (PMID 34833427, 2021). "The clinical benefit of small-molecule EGFR inhibitors on KRAS-mutant cancers is context-dependent." (PMID 34607583, 2021). "The role of the EGFR–CD44 axis in cancer progression might be the reason behind the limited success of targeting only EGFR as a therapeutic approach in cancer treatment." (PMID 33981532, 2021). "In another example of surface functionalized CDs, Zhu’s group functionalized porphyrin-based nitrogen-rich CDs with cetuximab for precisely targeting cancer cells with overexpression of epidermal growth factor receptor, and thus enhance the photoacoustic signals in tumors." (PMID 34064173, 2021).
cancer (continued). "These facts indicate that some cancer cells are still viable after exposure to EGFR TKIs." (PMID 34202566, 2021). "The EGFR is the target gene for many scientists trying to find a therapy for cancer." (PMID 34200663, 2021). "Decreasing PGD phosphorylation through EGFR signaling could dramatically attenuate cancer cells’ proliferation, growth and resistance to ionizing radiation." (PMID 34906147, 2021). "HSF1 inhibition by using HSF1 shRNAs or KRIBB11 decreased the expression of HSF1 downstream proteins, such as HSP70 and HSP27, and also decreased the expression of HSP90/HSP70/BAG3 client proteins, such as BCL2, MCL1, EGFR, MET, and AXL, causing apoptosis of EGFR-TKI-resistant cancer cells." (PMID 34203709, 2021). "On the other hand, cetuximab which targets the extracellular domain of epidermal growth factor receptor (EGFR) might promote activation of the immune response in CRC patients in addition to its direct action on cancer cells." (PMID 33916641, 2021). "In addition, glutamine (conditional EAAs) is known to be essential to cancer cells, and the glutamine-deprivation-induced cytostatic effect was inconsistent among the different EGFR-mutant NSCLC cells." (PMID 33450879, 2021). "Thus, a staining percentage score for EGFR expression was high in benign and atypical tumors but low in all malignant tumor samples evaluated." (PMID 34768783, 2021). "In addition, acquired resistance to anti-EGFR monotherapy has been reported in various types of cancers." (PMID 34207383, 2021). "Collectively, the results indicate that autocrine and paracrine EREG may mainly activate EGFR downstream pathways in various cancer TMEs that contribute to tumorigenesis." (PMID 34884633, 2021). "EGFR overexpression is also common in other cancers, such as lung and colon." (PMID 33540470, 2021). "An early application of this was the epidermal growth factor receptor (EGFR), abnormally activated in cancer, against which the two classes of anti-EGFR agents, monoclonal antibodies and low-molecular-weight tyrosine kinase inhibitors, showed antitumor activity in patients." (PMID 34834152, 2021). "13f is a more potent anti-cancer agent, which includes inhibition of proliferation by induced early apoptosis, inhibition of clonogenic ability and migration than Gefitinib by modulated EGFR signaling pathway in CCA." (PMID 33639651, 2021). "Furthermore, the substrate binding site of the kinase was also targeted by peptides to EGFR resistant cancer cell lines." (PMID 33670650, 2021). "Taken together, we found that EGFL6 could regulate cancer cell migration, invasion, proliferation and self-renewal by affecting EGFR and integrin receptor signaling." (PMID 33726836, 2021). "Although our population is enriched for “never smokers”, which explains the high incidence of EGFR mutations, the concordance between primary tumors and BMs does suggest the existence of cancer “stemness”." (PMID 33580130, 2021). "In addition, Soto-Gamez and colleagues have developed an innovative therapeutic approach to target the function of ADAM17 in EGFR activation and cancer progression." (PMID 33579029, 2021). "With myriad possibilities of gene mutations, it is evident that cancers do not respond to general therapy because of downstream malignancies or resistance to therapies like anti-EGFR drugs in CRC." (PMID 33596259, 2021). "Therefore, employing Au10Peptide5 as EGFR TKIs delivery results in inhibiting cancer cells through dual pathways." (PMID 34322025, 2021). "Further, it may contribute to rational drug design for novel targeted EGFR related cancer therapies." (PMID 33530424, 2021). "Importantly, low/moderate EGFR levels were found on this patient cancer material, in comparison to common HNSCC cell lines." (PMID 36405501, 2021). "In this study, we aimed to find new potential anti-cancer agents against EGFR-TK." (PMID 33921332, 2021). "Autophagy and cancer stem cells (CSCs) also contribute to resistance to EGFR target therapy." (PMID 34663410, 2021).
cancer (continued). "The epidermal growth factor receptor (EGFR) is an essential driver of oncogenic signalling, and EGFR inhibitors are some of the earliest examples of successful targeted therapies in multiple types of cancer." (PMID 34610265, 2021). "However, EGFRe1 knockdown in both cancer cell lines significantly downregulated EGFR mRNA expression, compared to control LNA-AS transfected cells." (PMID 34722266, 2021). "Oncogenic KRAS mutations were found in the absence of EGFR mutations in different histological cancer subtypes and in one case of an OSP." (PMID 34885191, 2021). "Thus, regulation of EGFR protein levels represents an effective potential strategy for anti-cancer therapy." (PMID 34689164, 2021). "However, there are notable exceptions to this rule such as EGFR’s ability to translocate to the nucleus as well as other organelles in cancer cells." (PMID 33673346, 2021). "EGFR, which is frequently mutated or overexpressed in cancer, was found to be amplified in 2/10 (20%) DSRCT tumors, and an EGFR CAR T cell trial for children and young adults with refractory/recurrent solid tumors (including DSRCT) is currently underway (NCT03618381)." (PMID 34869013, 2021). "On the contrary, glioblastoma and lung carcinoma cell line treatment with nanomolar concentrations of THC may even promote cancer cell growth, which depends on metalloproteinase and EGFR activity." (PMID 34503163, 2021). "Aberrant EGFR activation often leads to the progression of various diseases and cancers." (PMID 33996800, 2021). "We interrogated a large publicly available data resource derived from thousands of annotated drug response of cancer cell lines to examine co-occurring signatures of drug resistance and found that CTDs mostly appear to have co-occurring resistance with the EGFR-TKI gefitinib." (PMID 33850249, 2021). "The EGFR-ERK signaling pathway has been shown to regulate cancer cell migration." (PMID 33946151, 2021). "In addition, anakinra has been shown to overcome erlotinib (an EGFR inhibitor) resistance in a HNSCC mouse xenograft cancer model, suggesting its use as a possible strategy to overcome EGFR inhibitor resistance for HNSCC treatment." (PMID 35048046, 2021). "To determine whether pY sites of GAB1 and GAB2 exhibit the same pattern of response in other cellular contexts, we also treated other EGFR-driven cancer cell lines with SHP099." (PMID 33755016, 2021). "NGS and FISH analysis revealed EGFR amplification in the resistant cancer cells." (PMID 33471376, 2021). "Indeed, upon intravenous administration, PTX/miR-7 nanoparticles revealed anti-cancer properties in OvCa models through the inhibition of PTX-induced EGFR/ERK pathway." (PMID 34072348, 2021). "Based on the EGFR’s role in cancer and the availability of anti-EGFR inhibitors, patients of subtype II may benefit from anti-EGFR inhibitors." (PMID 34234737, 2021). "Researchers speculate that the efficacy of EGFR-targeting agents used in cancer therapy can be influenced by AREG." (PMID 33562468, 2021). "SKA3 acts as an oncogene by directly binding to EGFR and promoting cancer metastasis." (PMID 34059086, 2021). "EGFR is a receptor tyrosine kinase with a rich history in cancer pathogenesis." (PMID 33148698, 2021). "GE11 is a peptide that has been applied for targeting EGFR on the surface of cancer cells." (PMID 34943856, 2021). "It is plausible that SNPs altering EGFR gene expression, protein levels, or signaling may contribute to variable clinical outcomes and survival in cancer patients." (PMID 34070597, 2021). "Likewise, activation of FGFR signaling rendered EGFR-driven cancer cells resistant to EGFR inhibitors, and this EGFR resistance was overcome by FGFR inhibition." (PMID 34638374, 2021).
cancer (continued). "Moreover, precision medicine has enabled precise diagnosis-based medications, e.g., if the mCRC was EGFR-positive and RAS-wildtype, anti-EGFR antibody drugs such as cetuximab would be effective for cancer." (PMID 33562088, 2021). "Moreover, treatment of SCC-25 cells with Gef and its combination with DMU-214 resulted in a down-regulated mRNA level of EREG, which as a ligand of EGFR is known to contribute to the activation of the receptor and, therefore, cancer cells proliferation." (PMID 34201116, 2021). "For instance, mutations of Epidermal Growth Factor Receptor, EGFR/PI3K, loss of the tumor suppressor protein phosphatase and tensin homologue (PTEN), and mutations or amplifications of Akt itself enhance Akt’s signaling in cancer cells." (PMID 33916378, 2021). "EGFR inhibition is one of the key targets of cancer chemotherapy." (PMID 33777163, 2021). "In this study, we examined the anti-cancer effect of gefitinib (trade name “Iressa”), an orally active epidermal growth factor receptor (EGFR) tyrosine kinase inhibitor (TKI) on TGF-β-mediated EMT in NSCLC cells and the effect of its combination with integrin receptor antagonist cilengitide." (PMID 33967774, 2021). "Data for CT of other anti-cancer TT studied in elderly have been reviewed (anti-angiogenic treatment, anti EGFR, M-TOR inhibitors, BRAF and MEK inhibitors, C-KIT inhibitors, HER2 targeted therapies, tyrosine kinase inhibitors, or ALK inhibitors) and showed similar results that for younger patients." (PMID 34207200, 2021). "In fact, the EGFR is widely present in EVs from various cancer cell lines." (PMID 34283059, 2021). "Finally, reducing EGFR palmitoylation increases the sensitivity of multiple cancer cell lines to existing inhibitors of EGFR and downstream signalling effector pathways." (PMID 34610265, 2021). "This suggests that targeting EGFR pathways could be a promising solution for PDT clinical trials for patients with cancer metastasis." (PMID 34575510, 2021). "Therefore, targeting Rac is considered a viable strategy to overcome anti-EGFR/HER2 therapy resistance in cancer." (PMID 34074257, 2021). "Tetrahydropyrido[4,3-d]pyrimidine was found, by in vitro cytotoxic and enzymatic assays, to inhibit both ATX and EGFR with anticancer and antifibrotic activity superior to gefitinib, an EGFR inhibitor clinically used for the treatment of lung, breast and other cancers with overactive EGFR signaling." (PMID 33526777, 2021). "First, we analyzed the binding of nobiletin to the EGFR, as it is well-known in other cancer cells." (PMID 34576006, 2021). "Application of LM-based methods for absolute quantification of ρR values of EGFR or HER2 in overexpressing cancer cells, is prone to diverse artifacts and biases, often due to steric hindrance of the labels since the ρR may reach 103/μm2." (PMID 34831465, 2021). "PF299804 or dacomitinib is an EGFR inhibitor used in cancer therapeutics." (PMID 34071060, 2021). "To investigate possible crosstalk of integrin β4 with the EGFR in the promotion of cancer signaling, we first characterized EGFR-mediated β4 tyrosine phosphorylation in multiple benign and malignant epithelial cell lines derived from breast, colon and skin tissues." (PMID 33883672, 2021). "We also revealed that 1,2-NQ treatment and aberrant activation of EGFR–Akt signaling promote apoptosis resistance in a cancer cell line, which may correlate with carcinogenesis." (PMID 33705793, 2021). "Moreover, by lowering the level of endogenous EGFR in cancer cells, one can sensitize these cells to radiotherapy, which would lead to an enhancement of the therapeutic effect." (PMID 34064412, 2021). "Interestingly, monoclonal antibody and small molecule-based inhibitors of EGFR/ErbB receptors are now extensively used in the treatment of cancer." (PMID 34408653, 2021).
cancer (continued). "Although most clinical focus has been on EGFR and ERBB2 due to their aberrant activation in many human malignancies, overexpression of ERBB3 often co-occurs with EGFR or ERBB2 in many types of cancers such as breast, colorectal (CRC), gastric, ovarian, and pancreatic." (PMID 34843459, 2021). "These genes included well-known cancer-promoting factors, such as EGFR, WNT9A, and MAP2K2." (PMID 34272396, 2021). "First, they could accelerate EGFR turnover by ubiquitination, and decrease EGFR receptor density, allowing less concentration of cetuximab to exert cancer inhibitory effects." (PMID 33906293, 2021). "EGFR is a well-established therapeutic target; many small-molecule kinase inhibitors and monoclonal antibodies have been approved for treating several human cancers by the US FDA." (PMID 33801977, 2021). "Moreover, the potential relationship of LncRNA on the EGFR pathway in several cancers had been proven." (PMID 33799753, 2021). "Knockdown of CSC-regulating pathways involved in cancer stemness may augment sensitivity to current chemotherapy and targeted therapy like EGFR TKIs." (PMID 34680249, 2021). "Interestingly, when cancer cells were co-cultured with hepatocytes, the activation of the EGFR signaling pathway was inhibited." (PMID 34147083, 2021). "However, in the second decade of the 21st century, eleven EGFR-TKIs were approved for the treatment of different types of cancers." (PMID 34771085, 2021). "Conversely, AMPK was shown to suppress the activation of the EGFR in cancer cells, which indirectly suggests that AMPK may suppress the phosphorylation of Tyr10." (PMID 34748042, 2021). "EGFR results in cancer cell proliferation, aggressiveness and metastasis." (PMID 34754042, 2021). "Moreover, it has been determined that broad-spectrum HDAC inhibitors can synergize with EGFR inhibitors, leading to increased apoptosis in cancer cells and sensitization of resistant cells to EGFR inhibition." (PMID 33976119, 2021). "The functionally unknown EGFR gene is also responsible for gene amplification and is found to be prevalent in several types of cancer." (PMID 34764329, 2021). "Hence, our findings for the first time connect DR4 downregulation with the efficacy of osimertinib-based or EGFR-targeted cancer therapy, which is in contrast to the known function of DR4 as a pro-apoptotic protein." (PMID 33664875, 2021). "Moreover, CBD is a potent inhibitor of the EGF/EGFR pathway in cancer cells, which also inhibits the activation of the proinflammatory NFκB pathway." (PMID 33540902, 2021). "Mutations clustering around the ATP‐binding pocket of the tyrosine kinase domain lead to constituent, ligand‐independent activation of EGFR, which results in inappropriate activation of the antiapoptotic Ras signaling pathway and abnormal proliferation of cancer cells." (PMID 34977873, 2021). "Theoretically, EGFR-targeted NIR-PIT could be applied to other types of cancers with EGFR overexpression." (PMID 34064074, 2021). "The expression of EGFR has been found to be upregulated in cancer and EGFR is a major target for anticancer drug discovery as it inhibits apoptosis and promotes proliferation of cancer cells." (PMID 34069424, 2021). "Cancer cells often display upregulation of the EGFR signalling or receptor overexpression." (PMID 35127732, 2021). "Moreover, CD151 drives cancer progression depending on integrin α3β1 through EGFR signaling in NSCLC." (PMID 34976811, 2021). "EGFR endocytic trafficking towards recycling versus degradation routes is tightly intertwined with signaling intensity and therefore impact upon cell proliferation, survival and migration processes usually altered in cancer." (PMID 34298835, 2021). "EGFR plays an important role in cancer progression and regulates inflammation and oxidative stress." (PMID 34707493, 2021).